NOTCH1 (notch receptor 1)
Diseases named in the same sentence as NOTCH1 in open-access papers (continued):
Sharing a sentence is not in itself a finding about the gene and the disease.
ovarian carcinoma (continued). "Decreased levels of miR-9 have been linked to tumorigenesis of triple negative breast cancer and ovarian cancer were signaling pathways of NOTCH1 and NF-kB have been proposed to play a role in their tumorigenesis." (PMID 37081981, 2023). "For example, studies have shown that SNORD89 deteriorates the prognosis of ovarian cancer patients by regulating Notch1‐c‐Myc pathway to promote cell stemness and acts as an oncogene in ovarian tumorigenesis." (PMID 37488742, 2023). "All-trans retinoic acid (ATRA) inhibited Notch-1 expression in glioblastoma, breast and ovarian cancer cells, and NICD-1 in glioblastoma cells." (PMID 35408894, 2022). "SNORD89 enhances tumorigenesis via mediating the Notch1/c‐Myc pathway in patients with ovarian cancer." (PMID 35100495, 2022). "Ovarian cancer cells express Notch1, Notch2, Notch3, Notch4 and Jagged2, while ECs located in the ovary express Jagged1 and Dll1 and Dll4 ligands." (PMID 36430649, 2022). "SNORD89 is highly expressed in ovarian cancer stem cells and promotes dryness of ovarian cancer cells by regulating the Notch1-c-Myc pathway." (PMID 36566215, 2022). "Such a finding was also confirmed in another study, which revealed that miR-34 hinders the proliferation of human ovarian cancer cells by inducing autophagy and apoptosis, and inhibits cell invasion by targeting Notch1." (PMID 35265142, 2022). "TargetScan analysis showed Notch1 to be one of the targets of miR-34a, which was further validated by luciferase reporter assay in human ovarian cancer cells." (PMID 35265142, 2022). "The Notch1 pathway can promote drug resistance of cancer cells including gastric cancer cells, ovarian cancer cells, and prostate cancer cells." (PMID 35655918, 2022). "Among the specific cancer genes downregulated in the EV-RNA from the R0 group, NOTCH1 stands out for its specific role in ovarian cancer chemoresistance." (PMID 35892848, 2022). "In ovarian cancer, the overexpression of miR-34 mimic induced cell death and autophagy through downregulating Notch1, whereas Notch1 transfection reverted anti-proliferative effects of miR-34." (PMID 35887021, 2022). "In A2780 ovarian cancer cells, withaferin A inhibited Notch-1 and enhanced the therapeutic effect of Doxil, a liposomal preparation of doxorubicin." (PMID 35408894, 2022). "MiR-34 represses cell proliferation by facilitating apoptosis and autophagy and suppresses cell invasion by regulating Notch1 in ovarian cancer." (PMID 34690112, 2021). "For instance, SNORA72 displays high expression in ovarian cancer and promotes the maintenance of ovarian cancer stem cell stemness by activating the Notch1/c‐Myc pathway." (PMID 34047477, 2021). "The therapeutic activity of XH on ovarian cancer was due to downregulation of Notch1 and protein expression." (PMID 33923053, 2021). "In ovarian cancer, the antiproliferative effects of WA were related to abolished Notch1 and Notch3 expression and AKT signaling inhibition." (PMID 34680255, 2021). "Several recent studies have demonstrated that Notch 1 regulates PTEN/Akt signaling in ovarian cancer cells, hepatocytes and skeletal muscle cells." (PMID 33802884, 2021). "Growing evidence has suggested that Notch1 is important for tumor progression, chemoresistance and cancer stem-cell biology in ovarian cancer." (PMID 33802884, 2021). "Overexpression of miR-34a in ovarian cancer cells confirmed that down-regulation of Notch1 expression activated the apoptotic pathway and inhibited cell migration." (PMID 34319204, 2021). "In ovarian cancer, Notch3 and Notch1 usually activate multiple signaling pathways to participate in cancer development." (PMID 34277625, 2021). "A stable high expression or low expression of Notch1 in ovarian cancer cells was established by using lentiviral gene engineering." (PMID 32547317, 2020). "Recently, it has been reported that Notch1 signaling pathway is involved in the development and drug resistance of ovarian cancer." (PMID 32547317, 2020).
ovarian carcinoma (continued). "Ovarian cancer tissue had increased expression of Notch1, Snail, MMP-2, N-cadherin and Vimentin, but had decreased expression of E-cadherin." (PMID 32547317, 2020). "Dll4, Notch 1, Notch 3 or Jagged 1 are overexpressed in ovarian cancer suggesting that Notch signaling is primordial in ovarian cancer." (PMID 32014047, 2020). "In summary, stemness transformation of ovarian cancer cells can be activated by SNORA72 through the Notch1/c-Myc pathway." (PMID 33224949, 2020). "Firstly, ovarian cancer tissue showed an increased protein expression of Notch1, Snail, MMP-2, N-cadherin and Vimentin, but had decreased expression of E-cadherin." (PMID 32547317, 2020). "The previous studies, which explored the close relationship between Notch1 and its role on ovarian cancer, were controversial." (PMID 32547317, 2020). "The current study is to investigate the possible mechanisms of platinum-resistance in epithelial ovarian cancer mediated by Notch1." (PMID 32547317, 2020). "SNORD89 deteriorates the prognosis of ovarian cancer patients by regulating Notch1-c-Myc pathway to promote cell stemness and acts as an oncogene in ovarian tumorigenesis." (PMID 31395064, 2019). "In human tumour tissues, cisplatin‐resistant ovarian cancer group also showed high protein levels of Jagged1 and Notch1/2 compared with the cisplatin responsive group." (PMID 30993885, 2019). "Next, we assessed the effects of SNORD89 interference on the expression of c-Myc and Notch1 in ovarian cancer cells." (PMID 31395064, 2019). "The number of combinations of c-Myc and NOTCH1 will raise as the increased expression and then promoting the stemness phenotype and development of ovarian cancer." (PMID 31395064, 2019). "For example, NOTCH1 plays an important role in cisplatin resistance mechanism of head and neck squamous cell tumor, colorectal tumor, ovarian cancer, and other malignant tumors." (PMID 32038705, 2019). "Decreased expression levels of Oct-4, NOTCH1, and vimentin in quiescent sorted ovarian cancer spheroid cells can be reversibly restored after the quiescent spheroid cells reenter the cell cycle and form new colonies." (PMID 30319732, 2018). "Taken together, upregulation of Notch1 by c-Myc contributed to cell proliferation in ovarian cancer." (PMID 29423060, 2018). "Notch1, one of the Furin substrates, was upregulated by c-Myc, and Notch1 cleaved by Furin increased cell proliferation of high c-Myc-expressing ovarian cancer cells." (PMID 29423060, 2018). "Notch1 inhibition suppresses cell growth of ovarian cancer, indicating that Notch1 is a potential candidate for targeted therapy of ovarian cancer." (PMID 29423060, 2018). "In the present study, we provide evidence that LGR5 can promote ovarian cancer progression via Notch1 signaling in EOC." (PMID 29777575, 2018). "The expression of NICD was greatly reduced in ovarian cancer cell lines after treatment with Notch1 siRNA." (PMID 28030808, 2017). "Notch1 and NICD were frequently expressed in ovarian cancer cell lines and specimens, concluding that Notch1 plays a role in ovarian cancer proliferation." (PMID 28030808, 2017). "Down-regulation of Notch1 expression was significantly inhibit cell growth, induce G1 cell cycle arrest and induce cell apoptosis in A2780 ovarian cancer cells." (PMID 28415574, 2017). "In this research, we found that Notch1 was widely expressed in both epithelial ovarian cancers and benign tumours, while the ICSs of Jagged1 and NICD in ovarian cancer were higher than in benign ovarian tumour." (PMID 28030808, 2017). "There was not any significant different in the immunohistochemical scoring index (ICS) of Notch1 between ovarian cancer and benign ovarian tumour." (PMID 28030808, 2017).
ovarian carcinoma (continued). "In this context, HMGA1 over-expression was observed in epithelial ovarian carcinomas, while NOTCH1 has been correlated with ovarian cancer development and a poor prognosis." (PMID 29132324, 2017). "We next analyzed the relationship between the expression of Notch1 pathway and clinicopathologic factors of ovarian cancer." (PMID 28030808, 2017). "The over expressions of Dll4, Notch 1, Notch 3 or Jagged 1 suggest that Notch signalling plays a key role in angiogenesis in ovarian cancer." (PMID 28284219, 2017). "In order to confirm if γ-secretase in Notch1 pathway plays a role in the carcinogenesis of ovarian cancer, we detected the relative enzymatic activity of γ-secretase by dual-luciferase reporter assay system." (PMID 28030808, 2017). "We investigated the Notch1, Jagged1 and NICD immunohistochemical expression in all the 43 human ovarian cancer tissue specimens and 11 benign ovarian tumour tissue specimens." (PMID 28030808, 2017). "DAPT, a γ-secretase inhibitor, which reduces gamma-secretase in Notch1 signaling pathway was reported as a highly promising novel therapeutic drug candidate for ovarian cancer patient." (PMID 28415574, 2017). "The high level of Notch1 has also been revealed in ovarian cancer cell lines including OVCAR3, SKOV3 and CaOV3." (PMID 29104587, 2017). "Recently, a number of studies also demonstrated that Notch signaling pathway, especially Notch1 is important for maintaining cancer stem cells in ovarian cancer." (PMID 28415574, 2017). "In conclusion, we show that CSC characteristics in not only ovarian cancer cell lines but also primary CSCs are augmented in hypoxic condition, and NOTCH1 and SOX2 are important mediators of hypoxia in ovarian CSCs." (PMID 27489349, 2016). "Recent studies of NOTCH signaling in ovarian cancer have found a critical role of NOTCH1 in proliferation and metastasis of ovarian cancer cells." (PMID 27489349, 2016). "In our study, hypoxic treatment of ovarian cancer cells resulted in increased expression of NOTCH1 and generation of NICD1." (PMID 27489349, 2016). "Hypoxic treatment or overexpression of intracellular domain of NOTCH1 (NICD1) in ovarian cancer cells increased sphere formation, drug resistance, and expression of CSC-associated genes such as SOX2, ALDH, and ABC transporters." (PMID 27489349, 2016). "Gene expression analysis of CSC-enriched ovarian cancer populations, including sphere cells, side population, and high-grade serous ovarian cancer, showed increased expression of NOTCH1." (PMID 27489349, 2016). "In order to verify the relationship of Notch1 signaling and the differentiation of DC precursors in the ovarian cancer microenvironment, we added SKOV3 cultured supernatants into different DC precursor culture system." (PMID 27259477, 2016). "We found many potential biomarkers of platinum resistance in hypoxia including NOTCH1 which has been identified as a potential therapeutic target in ovarian cancer." (PMID 26205780, 2015). "Recent studies have indicated an association between NOTCH1 or NOTCH3 and cisplatin resistance in squamous head and neck and ovarian carcinomas and in EBV-associated naso-pharynx carcinomas, respectively." (PMID 25954607, 2015). "In one study of relative Notch1 expression in benign ovarian tissue and a spectrum of low- to high-grade ovarian carcinomas, Notch1 was rarely detected in benign tissue and its expression level correlated with increasing grade and clinical stage of disease." (PMID 25072022, 2014). "Wang and colleagues used IHC to study Notch1 levels in ovarian cancer specimens of various histological grades as well as patient-matched contralateral benign ovarian samples and normal ovarian tissues." (PMID 25366565, 2014).
ovarian carcinoma (continued). "Here, we report that the loss of miR-199b-5p due to progressive epigenetic silencing leads to the activation of the JAG1-mediated Notch1 signaling cascade, thereby leading to the development of acquired chemoresistance in ovarian cancer." (PMID 24659709, 2014). "According to our recent study, Notch signaling affects ovarian carcinomas and Notch1 expression correlates with metastasis, while Jagged1 expression correlates with tumor grade." (PMID 24932297, 2014). "For instance, T-ALL cells as well as ovarian cancer cells are characterized by activated Notch signaling; accordingly, down-regulation of Notch-1 by GSI contributes to cell growth inhibition and apoptosis in ovarian cancer cells." (PMID 22348144, 2012). "Inhibition of Notch-1 signalling by γ-secretase inhibitors slowed down cell-cycle progression and reduced the amount of eIF6 in lymphoblastoid and ovarian cancer cell lines." (PMID 22348144, 2012). "In ovarian cancer cell lines the expression of Notch was a strong expression of Notch 1-EC in A2780, an intermediate expression in OVCAR-3, but a lower expression level in IOSE-144." (PMID 16136053, 2005). "Notch 1 and Notch 1-EC protein was expressed in all ovarian cancers, borderline tumours and ovarian adenomas at similar levels." (PMID 16136053, 2005). "For instance, in ovarian cancer, exosomes derived from cancer-associated adipocytes have been shown to promote tumor angiogenesis and metastasis by transferring miR-199a-5p, which targets the Von Hippel-Lindau (VHL) and Notch1 genes." (PMID 39866229, 2025). "Gal3 has been reported to support stemness in ovarian cancer by activating the Notch1 signaling pathway, therefore we assessed the levels of intact and cleaved Notch1 (Notch1 intracellular domain (NICD)) in the ARK1 and 2 Gal3-CTRL and KO cells by immunoblotting." (PMID 38438589, 2024). "In the present study, NOTCH1 mutation promoted the migration and invasion of ovarian cancer cells in vitro and in vivo, and these effects could be attenuated by NOTCH1 inhibitor (LY3039478) treatment, especially in cells with NOTCH1 mutation." (PMID 36982170, 2023). "Furthermore, galectin-3 positively regulates Notch 1 signaling pathway in ovarian cancer cells and directly interacts with Notch 1 intracellular domain through its CRD." (PMID 36823664, 2023). "To determine whether STAT3 and NOTCH1 signaling pathways are implicated in CD109-induced drug resistance in ovarian cancer cells, we examined the effects of STAT3 and NOTCH1 inhibitors on CD109-induced drug resistance." (PMID 37373457, 2023). "For instance, reduction of KLF9 could facilitate stemness in ovarian cancer via Notch1/slug signalling." (PMID 37400979, 2023). "Through the Akt and Notch-1 signaling pathways, theaflavin-3,3′-digallate inhibited the angiogenesis in a human umbilical vein endothelial cell and a chick chorioallantoic membrane model, induced by human ovarian cancer cells (OVCAR-3)." (PMID 36386196, 2022). "Additionally, SNORA72 was shown to be able to activate the stem cell-like transformation of ovarian cancer cells through the Notch1/c-Myc pathway, which accelerated the occurrence of ovarian cancer." (PMID 35422067, 2022). "Moreover, in ovarian cancer, the overexpression of miR-34 mimic downregulated Notch1, and it induced cell death and autophagy, whereas Notch1 transfection reverted its anti-proliferative effects." (PMID 34680255, 2021). "Additionally, we also demonstrated that SNORA72 induced the stemness transformation of ovarian cancer cells by activating the Notch1/c-Myc pathway." (PMID 33224949, 2020). "We first examined whether TGF-β1–3 and Notch1 promoted the proliferation of ovarian cancer cells, because previous reports demonstrated that these substrates have both promotive and inhibitive effects on cancer cell proliferation." (PMID 29423060, 2018). "The Notch1-c-Myc regulatory loop may also be related to promoting cell proliferation in c-Myc-driven ovarian cancer." (PMID 29423060, 2018).
ovarian carcinoma (continued). "In addition, we found that Notch1 expression was upregulated by the c-Myc level in ovarian cancer cells." (PMID 29423060, 2018). "Moreover, Notch1 and c-Myc mRNA levels correlated in 18 cell lines including 16 ovarian cancer cell lines and HFFs (Pearson’s correlation, R = 0.526)." (PMID 29423060, 2018). "Furthermore, depletion of Notch1 led to growth inhibition of ovarian cancer cell lines, which provide evidence for target therapy of ovarian cancer by inhibiting Notch pathway." (PMID 28030808, 2017). "The active form of Notch 1, the Notch 1 intracellular domain (NICD), was detected in ovarian cancer cell lines, ovarian cancer specimens and may led to growth inhibition of ovarian cancer cells upon depletion of Notch 1 by Notch 1 siRNA." (PMID 28415574, 2017). "Notch1 NICD was reported to be an independently poor prognostic factor in ovarian cancer patients." (PMID 28415574, 2017). "In addition, increased expression of NOTCH1 was identified as an independent prognostic factor for poor survival of epithelial ovarian cancer patients." (PMID 27489349, 2016). "We were interested that galectin-3 regulates the Notch1 signaling pathway in ovarian cancer stem cells because Notch pathway genes might be important therapeutic targets for CSCs and many new agents targeting the Notch pathways have entered clinical trials." (PMID 27626163, 2016). "Studies of the role of Notch1 in ovarian cancer indicated that mRNAs of the Notch pathway genes were highly expressed in ovarian adenocarcinomas, borderline tumors, and adenomas, and NCID1 overexpression increased cell proliferation and colony-formation capacity." (PMID 27626163, 2016). "Finally, the natural compounds xanthohumol and withaferin A inhibited cell growth and induced apoptosis and cell cycle arrest in ovarian cancer cell lines through downregulation of Notch1 (withaferin A and xanthohumol) and Notch3 (withaferin A)." (PMID 25366565, 2014). "In contrast, IHC analyses of Notch1 expression in ovarian cancer have produced variable results." (PMID 25366565, 2014). "In contrast, activating Notch1 signaling by JAG1 or repressing miR-199b-5p by anti-miR-199b-5p could induce the activity of JAG1-Notch1 signaling in ovarian cancer cells." (PMID 24659709, 2014). "In addition, Notch1 and Notch3 RNA transcript and protein are highly expressed in ovarian carcinomas and elevated expression correlates with resistance to chemotherapy and decreased survival." (PMID 25072022, 2014). "Furthermore, we demonstrate a proliferative and survival advantage of stably Notch 1-IC (intracellular domain) transfected A2780 ovarian carcinoma cells." (PMID 16136053, 2005). "In this study, we found that NOTCH1 mutation was detected only in FDOVL cells, and the donor left pelvic lymph node from which they were derived, indicating that NOTCH1 mutation may be one of the driving events for lymph node metastasis in ovarian cancer." (PMID 36982170, 2023). "In cervical cancer, Notch1 has been reported to lead to changes in migration and invasion by regulating Rhoc and it has also been found to make similar phenotypic contributions with Rhoc in some other cancers such as non-small-cell lung cancer and ovarian cancer." (PMID 35955961, 2022). "We hypothesized the Notch1 gene as a therapeutic target by using miR-34a to knock down its expression, thereby inducing Bcl-2/Caspase-3 signaling pathway mediated apoptosis and inhibiting the growth of ovarian cancer." (PMID 34319204, 2021). "Whether miR-34a/Notch1 is also regulated by circASH2L in ovarian cancer needs further study." (PMID 33330483, 2020). "However, there is limited report about the application of Notch1 inhibitor in ovarian cancer." (PMID 32547317, 2020).